MYOM2 (myomesin 2)
Description:
Major component of the vertebrate myofibrillar M band. Binds myosin, titin, and light meromyosin. This binding is dose dependent.
Synonyms: TTNAP
Tractability: No criterion of Open Targets' tractability assessment is met for any kind of drug.
Gene: Protein-coding gene on chromosome 8 (2,044,682 to 2,165,552, forward strand). Ensembl gene ENSG00000036448.
Subcellular location: Cytoplasm, myofibril, sarcomere, M line
Subcellular location (Human Protein Atlas): Mitochondria
Gene Ontology:
Molecular function: kinase binding; protein binding; structural constituent of muscle
Biological process: sarcomere organization; muscle contraction; extraocular skeletal muscle development
Cellular component: mitochondrion; M band
Genetic constraint (gnomAD): Loss-of-function variants: 253 observed, 191.84 expected, observed/expected ratio (o/e) 1.32, 90% interval 1.19 to 1.46. The synonymous counts are far from expectation, so gnomAD's model fits this gene poorly and the ratio says little. Missense variants: 2,783 observed, 2,002.9 expected, observed/expected ratio (o/e) 1.39, 90% interval 1.35 to 1.43. Synonymous variants: 981 observed, 785.04 expected, observed/expected ratio (o/e) 1.25, 90% interval 1.18 to 1.32.
Homologues: Orthologues: macaque MYOM2 (97% identical), chimpanzee MYOM2 (94% identical), pig MYOM2 (89% identical), mouse Myom2 (89% identical), rat Myom2 (89% identical), dog MYOM2 (88% identical), rabbit MYOM2 (86% identical), guinea pig MYOM2 (85% identical), tropical clawed frog myom2 (68% identical), zebrafish myom2a (48% identical), Caenorhabditis elegans C34F6.10 (12% identical), Drosophila melanogaster mtgo (11% identical). Paralogues in human: MYOM1 (46% identical), MYOM3 (40% identical), MYBPC3 (17% identical), MYBPC1 (15% identical), OBSL1 (15% identical), MYBPC2 (14% identical), FNDC3A (14% identical), FNDC3B (14% identical), IGSF22 (13% identical), MYBPH (8% identical), MYBPHL (5% identical).
Diseases named in the same sentence as MYOM2 in open-access papers:
MYOM2 is named in the same sentence as 177 diseases in open-access papers, as found by Europe PMC text mining. Sharing a sentence is not in itself a finding about the gene and the disease. The quoted sentences say what the papers report.
breast carcinoma (7 papers, 2010 to 2024). "MYOM2 has been previously been observed to be downregulated in breast cancer patients, as determined by multiplex RT-PCR." (PMID 34884649, 2021). "Loss of the p-arm of chromosome 8 is frequently observed in breast, prostate, and other types of cancers, and among the genes located close to D8S264 is MYOM2, whose expression is downregulated in breast cancer." (PMID 20955588, 2010). "Downregulated MYOM2 was observed in a majority of clinical cases of breast cancer, however, the role of MYOM2, ADAMTSL2, and LARS in HCC development and prognosis remains unclear." (PMID 36276270, 2022). "Among them, CCNE1 and KRT20 were of high expression in BRCA1/2-mutant breast cancer, and ALB and MYOM2 were of low expression." (PMID 31998560, 2020).
hypertrophic cardiomyopathy (4 papers, 2016 to 2023). A condition in which the myocardium is hypertrophied without an obvious cause. "Although studies have shown that myomesin 2 (MYOM2) mutations can lead to hypertrophic cardiomyopathy (HCM), a common cardiovascular disease that has a serious impact on human life, the effect of MYOM2 on cardiac function and lifespan in humans is unknown." (PMID 36554435, 2022). "Editor's choice:MYOM2 plays a critical role in establishing or maintaining robust heart function, and is a candidate gene for heart diseases, such as hypertrophic cardiomyopathy and Tetralogy of Fallot." (PMID 33033063, 2020). "Therefore, MYOM2 may be important for hypertrophic cardiomyopathy and Tetralogy of Fallot." (PMID 37239897, 2023). "In this study, we identified mutations in myomesin 2 (MYOM2) in patients with Tetralogy of Fallot (TOF), the most common cyanotic heart malformation, as well as in patients with hypertrophic cardiomyopathy (HCM), who do not exhibit any mutations in the known disease genes." (PMID 33033063, 2020).
periodontitis (4 papers, 2020 to 2024). An acute or chronic inflammatory process that affects the tissues that surround and support the teeth. "MYOM2 was the only significantly up-regulated gene in localized invasive periodontitis, suggesting that it was associated with inflammation." (PMID 38977917, 2024). "One report showed that MYOM2 was the only significantly up-regulated gene in localized invasive periodontitis, suggesting that it was associated with inflammation." (PMID 33281116, 2020). "Among them, MYOM2 and TLR2 genes were significantly upregulated in patients with periodontitis in comparison to healthy controls (p = 0.032 and p = 0.003, respectively), confirmed by RT-PCR." (PMID 36233348, 2022).
prostate carcinoma (3 papers, 2021 to 2024). A carcinoma that arises from epithelial cells of the prostate gland. "We observed significant hypermethylation in 4 of the 10 target genes (MAN1A1, EPB41, HSD17B13, and MYOM2) in primary prostate cancer patient tumors (n = 503) compared to normal prostatic samples (n = 50) (p ≤ 0.05)." (PMID 34884649, 2021). "Lastly, we observed that decreased expression of MYOM2 correlates with decreased overall survival in prostate cancer patients." (PMID 34884649, 2021).
arthrogryposis (2 papers, 2020). A rare, non-progressive congenital disorder characterized by multiple joint contractures which are present at birth. "In addition, the results of genomic screening represented MYOM2 mutations was probably causative for arthrogryposis." (PMID 33281116, 2020).
cardiac hypertrophy (2 papers, 2021 to 2025). "An animal model of cardiac hypertrophy driven by the thyroid hormone (T3) in rats showed that the downregulated MYOM2 causes significant contractile dysfunction (P < 0.05)." (PMID 34158603, 2021). "M-protein (myomesin-2) encoded by MYOM2 or total myomesin is downregulated in cardiac hypertrophy in rats, in acute myocardial infarction (AMI) patients, or in chronic heart failure." (PMID 34158603, 2021).
cardiomyopathies (2 papers, 2020 to 2022). "In summary, this study showed novel rare, and probably disease-relevant, mutations in the sarcomere gene MYOM2 in patients with TOF and HCM, in particular for cardiomyopathy patients." (PMID 33033063, 2020).
diffuse large B-cell lymphoma (2 papers, 2020 to 2025). "Study had revealed that in relapsed/refractory diffuse large B-cell lymphoma patients, late oncogenic events was composed of clonally represented recurrent mutations/gene alterations including MYOM2." (PMID 33281116, 2020).
dilated cardiomyopathy (2 papers, 2016 to 2019). Cardiomyopathy which is characterized by dilation and contractile dysfunction of the left and right ventricles. "Previous studies have reported that over expression of EH-myomesin (MYOM2 isoform) served as a biomarker for dilated cardiomyopathy and TNF-α was up-regulated during brief myocardial ischemia, or coronary occlusion." (PMID 31195969, 2019).
hepatocellulare carcinoma (2 papers, 2024 to 2025). "MYOM2 involved in the process of the hepatocellulare carcinoma prognosis and immune infiltration." (PMID 38977917, 2024).
tuberculosis (2 papers, 2024). A chronic, recurrent infection caused by the bacterium Mycobacterium tuberculosis. "Furthermore, MYOM2 has also been identified in NK cell subset in single-cell transcriptomics in tuberculosis, and Alzheimer disease." (PMID 39085199, 2024).
alcohol dependence (1 paper, 2020). Physical and psychological dependence on alcohol. "Myomesin 2 (MYOM2) encodes a major protein in muscle tissue and was nominally associated with nicotine and alcohol dependence in Australian and Dutch populations." (PMID 31936517, 2020).
Arrhythmia (1 paper, 2025). Any cardiac rhythm other than the normal sinus rhythm. "Moreover, flies with a W1118 MYOM2 mutation presented with arrhythmias, which could be ameliorated by exercise." (PMID 40306862, 2025).
atherosclerosis (1 paper, 2024). A disease characterized by the build-up of fatty material and calcium deposition in the arterial wall resulting in partial or complete occlusion of the arterial lumen. "MYOM2 encodes a major component of the vertebrate myofibrillar M band, and hypomethylated CpG sites of MYOM2 have previously been reported to be associated with atherosclerosis-related phenotypes." (PMID 38927450, 2024).
chronic heart failure (1 paper, 2021). "In addition, it has been reported that myomesin (encoded by both MYOM1 and MYOM2) protein levels decrease in acute ischemia and in chronic heart failure." (PMID 34158603, 2021).
dengue (1 paper, 2019). "In addition, host genetic markers, such as the genes LOC286087, MYOM2, CACNA2D3, PSPH, SMAD5, SLC4A4D, and CD244 molecule, with reduced expression in DHF than in DF can be used as predictors of severe dengue." (PMID 31192066, 2019).
heart attack (1 paper, 2021). "Myomesin-2 showed decreased expression in multiple heart diseases or heart attack." (PMID 34158603, 2021).
muscle disorders (1 paper, 2024). "Mutations or dysregulation of MYOM2 can affect muscle strength and may be implicated in various muscle disorders." (PMID 38938033, 2024).
osteosarcoma (1 paper, 2024). A usually aggressive malignant bone-forming mesenchymal neoplasm, predominantly affecting adolescents and young adults. "Six of these genes are increased (MYOM2, VEGFA, MUC1, IHH, GLI1 and GRIA1) and seven are decreased (VCAM1, EGFR, GPC3, IGF2, GNG12, GNGT1 and C3) in localized patients with poor prognosis that either relapse or die due to osteosarcoma." (PMID 38538763, 2024).
ventricular septal defect (1 paper, 2020). The presence of a defect (opening) in the septum that separates the two ventricles of the heart. "As with many CHD cohorts in general, the variety of CHDs with MYOM2 mutations in the PCGC study was very wide, comprising complex heterotaxias, such as double outlet RV, as well as isolated simple atrial and ventricular septal defects." (PMID 33033063, 2020).
infection (119 papers, 2007 to 2026). The state of being infected such as from the introduction of a foreign agent such as serum, vaccine, antigenic substance or organism. "Genes encoding protein components of the cytoskeleton (NEB, MYOM2, MYOZ1, and MYBPC1) and surfactant proteins (A1, C, and D) were among the most significantly downregulated genes upon infection with swH1N1." (PMID 39247193, 2024).
tumor (54 papers, 1995 to 2026). "Similarly, MYOM2 overexpression may also mediate the malignant phenotype of tumor cells by affecting the inflammatory response of TME." (PMID 33281116, 2020).
cardiovascular diseases (3 papers, 2022 to 2023). "Remarkably, an increasing number of reports is linking all three myomesin proteins and particularly myomesin-2 to serious cardiovascular diseases suggesting that this protein family could be more important than originally thought." (PMID 35255917, 2022).
heart diseases (3 papers, 2020 to 2022). "In summary, our results suggest that MYOM2 not only plays a critical role in maintaining robust heart function but may also be a candidate gene for heart diseases such as HCM and TOF, as it is clearly involved in the development of the heart." (PMID 33033063, 2020).
myopathies (3 papers, 2023 to 2025). "For example, MYL1, MYOM2, TRIM63 and PSMD4 have been broadly associated with myopathies but not directly to LVNC or DCM yet, and could therefore be considered as potential targets to investigate." (PMID 37644440, 2023).
MYOM2 also shares sentences with these, for which no sentence is quoted: myeloma (165 papers); multiple myeloma (93); POEMS syndrome (36); endocrinopathy (34); monoclonal gammopathy (34); polyneuropathy (32); anemia (28); plasma cell dyscrasias (28); viral infection (28); COVID-19 (27); Hypercalcemia (24); skin changes (23); cancer (22); renal failure (18); plasmacytoma (15); rheumatic fever (13); rheumatic heart disease (10); kidney disease (9); amyloidosis (8); neuropathy (8); peripheral neuropathy (8); pharyngitis (7); streptococcal infection (7); Autoimmunity (6); influenza (5); lymphoma (5); psoriasis (5); autoimmune disease (4); hematologic malignancies (4); Lymphadenopathy (4).
A further 122 diseases each share a sentence with MYOM2 in 4 papers or fewer.